LRRC55 (leucine rich repeat containing 55)
Description:
Auxiliary protein of the large-conductance, voltage and calcium-activated potassium channel (BK alpha). Modulates gating properties by producing a marked shift in the BK channel's voltage dependence of activation in the hyperpolarizing direction, and in the absence of calcium.
Synonyms: FLJ45686
Tractability: Small molecule: it belongs to a druggable protein family. Antibody: UniProt places it where antibodies can reach, with medium confidence; UniProt predicts a signal peptide or a membrane-spanning region; its Gene Ontology location is reachable by antibodies, with medium confidence.
Gene: Protein-coding gene on chromosome 11 (57,181,747 to 57,191,717, forward strand). Ensembl gene ENSG00000183908.
Subcellular location: Cell membrane
Gene Ontology:
Molecular function: potassium channel activator activity; transmembrane transporter binding; voltage-gated potassium channel activity
Biological process: positive regulation of voltage-gated potassium channel activity; potassium ion transmembrane transport
Cellular component: voltage-gated potassium channel complex; plasma membrane
Genetic constraint (gnomAD): Loss-of-function variants: 11 observed, 19.97 expected, observed/expected ratio (o/e) 0.55, 90% interval 0.35 to 0.91. The upper end of that interval is the gene's LOEUF score, 0.91, which puts it in group 3 of 6, group 1 being the genes least tolerant of losing a copy. Missense variants: 358 observed, 397.66 expected, observed/expected ratio (o/e) 0.9, 90% interval 0.82 to 0.98. Synonymous variants: 188 observed, 172.12 expected, observed/expected ratio (o/e) 1.09, 90% interval 0.97 to 1.23.
Homologues: Orthologues: chimpanzee LRRC55 (100% identical), macaque LRRC55 (97% identical), rabbit LRRC55 (97% identical), dog LRRC55 (96% identical), mouse Lrrc55 (95% identical), rat Lrrc55 (94% identical), pig LRRC55 (93% identical), guinea pig LRRC55 (92% identical). Paralogues in human: TPBGL (29% identical), LRRN2 (28% identical), SLIT2 (28% identical), SLIT3 (27% identical), LINGO2 (26% identical), LRFN3 (26% identical), LINGO1 (26% identical), SLIT1 (26% identical), LRFN1 (25% identical), TLR9 (25% identical), LRFN5 (24% identical), LRFN2 (24% identical), and 13 more.
Diseases named in the same sentence as LRRC55 in open-access papers:
LRRC55 is named in the same sentence as 6 diseases in open-access papers, as found by Europe PMC text mining. Sharing a sentence is not in itself a finding about the gene and the disease. The quoted sentences say what the papers report.
depression (1 paper, 2018). "But it is possible that the BK channel and LRRC55 protein are involved in depression and stress." (PMID 29370300, 2018).
epilepsy (1 paper, 2021). A brain disorder characterized by episodes of abnormally increased neuronal discharge resulting in transient episodes of sensory or motor neurological dysfunction, or psychic dysfunction. "Other genes with CNV losses that have an indirect relation to epilepsy are RYR3, CDH13, PCDH9, and LRRC55." (PMID 33557955, 2021).
Nephropathy (1 paper, 2025). A nonspecific term referring to disease or damage of the kidneys. "Despite these significant findings, our study does not explore the role of the NFATc3/LRRC55/BK channel axis in other types of nephropathy, necessitating further research to validate its broader implications." (PMID 40520074, 2025).
renal fibrosis (1 paper, 2025). A final common manifestation of a wide variety of chronic kidney diseases characterized by glomerulosclerosis and tubulointerstitial fibrosis. "Masson's staining revealed extensive renal fibrosis, which was further aggravated in the LRRC55‐overexpression group, whereas fibrosis was significantly alleviated in the NFATc3‐knockdown group." (PMID 40520074, 2025).
renal diseases (1 paper, 2025). "Not only does this research contribute to unveiling the molecular mechanisms of podocyte damage in MN, but it also provides new insights into the synergistic effects of NFATc3/LRRC55/BK channels in the pathophysiology of renal diseases." (PMID 40520074, 2025). "Furthermore, targeted interventions against the NFATc3/LRRC55/BK channel axis may represent novel therapeutic approaches for MN and other related renal diseases, enhancing the quality of life for patients with renal diseases and slowing the progression of renal failure." (PMID 40520074, 2025).
LRRC55 also shares sentences with these, for which no sentence is quoted: membranous nephropathy (1 paper).